BRCA1 (BRCA1 DNA repair associated)
Diseases named in the same sentence as BRCA1 in open-access papers (continued):
Sharing a sentence is not in itself a finding about the gene and the disease.
breast cancer (continued). "The receptor landscape of BRCA1 mutant breast cancers shows typical ER-alpha negativity." (PMID 41514592, 2025). "Moreover, BRCA1 methylation promoted DNA homologous recombination repair activity and improved the breast cancer cells’ defense against IR." (PMID 40001488, 2025). "Among HER2 + stage I-III (N = 95) and stage IV (N = 78) breast cancers, the most frequent alterations, other than HER2 amplification, were PIK3CA mutations (26% vs 41.0%), followed by BRCA1/2 (6.3% vs 6.4%), ESR1 (1.1% vs 3.9%) mutations, and PD-L1 amplification (1.1% vs 0%)." (PMID 40421962, 2025). "However, the histopathology of the breast cancers of the BARD1 mutation carriers and BRCA1/2 mutation carriers showed certain distinguishing characteristics." (PMID 40805222, 2025). "When BRCA1 is inactivated, breast cancer cells become hypersensitive to DNA damage." (PMID 41155174, 2025). "There is also a report of LGASC occurring in a patient with a BRCA1 germline mutation, suggesting possible overlap with other basal-like breast cancers, though this association remains rare and not well characterized." (PMID 41301002, 2025). "These genes are known to regulate important mechanisms concerning cell growth and DNA damage repair; thus, a mutation in BRCA1 and BRCA2 is often related to genomic instability, as cells continue to proliferate despite having DNA damage, which promotes breast cancer." (PMID 40227634, 2025). "Future studies should investigate the contribution of germline mutations of BRCA1 and BRCA2 genes in a larger case-control cohort study of Brunei breast cancer population to confirm and further investigate the contribution of these germline mutations to breast cancer risk." (PMID 40531958, 2025). "The strength of this study lies in its first-time investigation of AMH level changes in BRCA1/2-mutated versus non-mutated young breast cancer patients, both at baseline and during NAC, alongside tumor size changes." (PMID 40220108, 2025). "A study in an Australian population examined the familial predisposition to breast and ovarian cancer in multiple multi-generational breast cancer families without BRCA1/2 mutations." (PMID 41296379, 2025). "Among the genetic factors, pathogenic variants in the BRCA1 and BRCA2 genes are critical, which contribute to the development of malignancy and of hereditary breast ovarian cancer syndrome, which accounts for 5–10% of all breast cancer cases." (PMID 40870889, 2025). "Our study suggests that active breast cancer treatment may be a key reason for deferring RRSO, further underscoring the essential role of tailored counseling and longitudinal support for BRCA1/2 mutation carriers." (PMID 40862027, 2025). "While BRCA1 and BRCA2 remain the most well-established genes linked to breast cancer risk, restricting testing to these two genes may overlook other clinically relevant mutations." (PMID 40800071, 2025). "Indeed, in a phase 2 randomized trial of BRCA1/2 mutated, locally advanced or metastatic non-HER2-positive breast cancer (NCT02849496), 78 patients are divided into two cohorts, one treated with Olaparib, and the other treated with Olaparib plus atezolizumab." (PMID 40830526, 2025). "Thus, it can be seen that BRCA1/2 gene screening is essential for the prevention and early detection of hereditary breast cancer/ovarian cancer." (PMID 40530017, 2025).
breast cancer (continued). "Exon sequencing of breast cancer patients with the familial BRCA1/2 mutation identified nonsense mutations in the DCLRE1C gene, suggesting its role in breast cancer." (PMID 41154337, 2025). "However, in our study group of 100 breast cancer cases, the detected methylation levels ranged from 4 to 25% and were lower than the expected ~ 50% (corresponding to allelic methylation of BRCA1 gene)." (PMID 40495194, 2025). "Some studies report BRCA1 loss in breast cancer as a marker of aggressiveness, though it is not always linked to tumor size or nodal status." (PMID 41373491, 2025). "The proportions of DCCHs with claims for breast cancer-related service fees were 15.2% (range: 0.0%–50.0%) for cancer genome profiling tests, 62.0% (range: 0.0%–100.0%) for cancer BRCA1/2 genetic tests, and 92.8% (range: 60.0%–100.0%) for patient support system enhancement." (PMID 40753278, 2025). "Since the discovery of synthetic lethal interaction between inhibition of poly(ADP-ribose) polymerase (PARP) and BRCA1 or BRCA2 mutation, clinically approved PARP inhibitors (PARPi) have shown promising activity in the treatment of BRCA1/2 mutated breast cancer." (PMID 41359628, 2025). "Nonetheless, in germline BRCA1/2 (gBRCA1/2)-mutated HER2-negative advanced breast cancer, talazoparib did not significantly improve overall survival over chemotherapy." (PMID 41155174, 2025). "Somatic mutations in BRCA1 or BRCA2 were detected in 3 (6%) and 4 (8%) patients, respectively, and 59% of patients had hormone receptor-positive, human epidermal growth factor receptor 2-negative breast cancer." (PMID 39839709, 2025). "Besides narrowing disparities between which groups of patients diagnosed with breast cancer are evaluated for testing, disparities between groups tested for BRCA1/2 must be addressed as well." (PMID 40123843, 2025). "However, relatively limited research has been conducted to investigate the efficacy of PARPi therapy in BRCA1/2 wild‐type breast cancer." (PMID 39778077, 2025). "For example, BRCA1 and BRCA2 mutations predispose both men and women to breast cancer." (PMID 41589155, 2025). "Additional promoter hypermethylation analysis of these four cases revealed that a breast cancer sample harboring a GIS of 62 harbored a DNA promoter hypermethylation in the vicinity of the BRCA1 transcriptional start site, while the remaining three cases displayed no hypermethylation." (PMID 40278800, 2025). "As enrichment of both DCAF8L1 and DCAF8L2 is observed in certain human breast cancer cells, these factors may promote carcinogenesis via negative regulation of BRCA1 and BARD1." (PMID 41009605, 2025). "Besides BRCA1 and BRCA2 mutations that markedly increase breast cancer risk, hundreds of low- and moderate-risk susceptibility variants have been identified, including caspase-8 (rs2293554, rs6723097,), TIMP-2 (rs7501477), and FSCN1 (rs56156320, rs3801004,)." (PMID 39614126, 2025). "Women who carry BRCA1 and/or BRCA2 pathogenic variants develop breast cancer at a mean age of 45." (PMID 40862808, 2025). "In WT patients, any DNA repair deficit (if present) would only affect breast cancer cells due to somatic BRCA1/2 mutations, explaining the lack of correlation between AMH decrease and tumor size reduction." (PMID 40220108, 2025). "This was largely driven by the increased incidence of TNBC which accounted for 56% of BRCA1 carriers with T1N0 breast cancer (90% of whom received chemotherapy), while only 15.6% of BRCA2 and 40% of PALB2 carriers had T1N0 TNBC (of which 80% and 100% received chemotherapy, respectively; eTable 1)." (PMID 40275390, 2025). "Data from one study show a protective role of breastfeeding against BRCA1-mutated breast cancer, but there is no protection for those with BRCA2 mutations." (PMID 41002733, 2025). "BRCA1 mutated breast cancers are negative for estrogen receptor (ER), progesterone receptor (PR), and human epidermal growth factor receptor 2 (HER2) and are classified as TNBC." (PMID 39621070, 2025).
breast cancer (continued). "Here, we searched for potential drivers based on germline DNA analysis from a cohort consisting of patients with early-onset breast cancer negative for BRCA1/BRCA2 mutations." (PMID 40261702, 2025). "Application to female breast cancer in non‐BRCA1/2 families." (PMID 40500950, 2025). "Among BRCA1/2 carriers, we found a statistically significant risk-reducing effect on breast cancer according to BRRM (with or without RR-BSO) (adjusted HR 0.06, CI 0.02–0.25), but not according to RR-BSO (adjusted HR 1.31, CI 0.90–1.91)." (PMID 40974500, 2025). "Notably, while BRCA1 and BRCA2 mutations are predominantly associated with breast cancer, this study detected BRCA2 protein in the lung cancer model, suggesting a potential, although lower, role of this protein in lung cancer." (PMID 40584122, 2025). "Testing for BRCA1 and BRCA2 mutations has become standard practice for females with breast cancer in their families, but other genetic abnormalities or variations may also be relevant in therapeutic settings." (PMID 40735254, 2025). "Association analyses did not reveal any correlation between rs799905 and BRCA1 promoter methylation and breast cancer risk." (PMID 40495194, 2025). "In breast cancer, BRCA1/2 germline alterations (7.0%) were more prevalent than somatic (3.2%)." (PMID 40420266, 2025). "To explore the applicability of OFD1 inhibition in other BRCA-associated cancer types with BRCA1/2 wild-type genotypes, we generated OFD1-inducible knockdown cell lines in MDA-MB231 breast cancer cells, PC3 prostate cancer cells, and A2780 ovarian cancer cells." (PMID 40764600, 2025). "Hispanic women with breast cancer were 2.58 times as likely as non-Hispanic women to carry a P/LP germline BRCA1 mutation than BRCA2 mutation." (PMID 40952741, 2025). "We compared gene expression profiles between breast cancer samples with BRCA1 promoter hypermethylation (n = 1) and those with promoter deletion (n = 16) to assess whether the mechanism of BRCA1 inactivation influences downstream gene expression." (PMID 40870889, 2025). "BRCA1 and BRCA2 are the most frequently found genes that increase the risk of breast cancer." (PMID 40286038, 2025). "The two breast cancer genes BRCA1 and BRCA2 are crucial in the DNA repair process." (PMID 39745016, 2025). "This trend may be partially explained by the fact that BL reconstructions are often chosen by patients with genetic or familial risk factors, such as BRCA1 or BRCA2 mutations, which are linked to an earlier onset of breast cancer." (PMID 40004590, 2025). "The most well-known genes are those related to breast cancer 1 and 2 (BRCA1 and BRCA2)." (PMID 40940924, 2025). "We found a coordinated behavior between BRCA1 and BRCA2 in breast cancer and observed BRCA1’s crypt-restricted expression in normal colorectal tissue, which may underlie its well-known tissue specificity." (PMID 41373491, 2025). "Building on these findings, our study investigated whether somatic inactivation of BRCA1 through promoter deletion or methylation, leading to one inactive somatic copy of the gene, correlates with enhanced survival in breast cancer patients." (PMID 40870889, 2025). "The MLPA testing was performed on 36 fresh frozen breast cancer samples to assess BRCA1 status." (PMID 40870889, 2025).
breast cancer (continued). "A key strength of our study is the high number of BRCA1/2 carriers, approximately 10 times higher than in the previous Danish BRCA1/2 cohort and considerably larger compared with other studies that examine the effects of BRRM on breast cancer incidence in BRCA1/2 cohorts." (PMID 40974500, 2025). "A family history of breast cancer was reported in 26.09% of cases, though BRCA1/2 mutation testing was not performed." (PMID 40248551, 2025). "Patients diagnosed with breast cancer and their affected family members (FMs) who are also found to carry BRCA1/2 PGVs are eligible for measures proven to prevent and diagnose earlier breast cancer (including second breast cancers) and other BRCA1/2-associated cancers." (PMID 40123843, 2025). "The recommended surveillance is based on current UKCGG guidelines, including an anticipated change in guidance, implemented in April 2025, recommending that all individuals with a GPV in BRCA1/BRCA2/PALB2 are eligible for enhanced breast cancer surveillance from the age of 25 years." (PMID 41159931, 2025). "The next step was to decide whether these similarities depended on mutations in the breast cancer susceptibility genes, BRCA1 or BRCA2, by comparisons to sporadic breast cancers." (PMID 39885374, 2025). "At the molecular and protein levels, BARD1 shows a significant degree of structural and functional similarity to BRCA1, and breast cancers occurring in individuals with BARD1 germline PVs exhibit a similar somatic gene expression profile to those with BRCA1 pathogenic variants." (PMID 40805222, 2025). "In addition, combinative treatment using a glutathione transferase (GSTP-1) inhibitor-derived RAPTA compound (RAPTA-EA1) and olaparib significantly suppressed the expression levels of BRCA1 protein in triple-negative BRCA1 wild-type breast cancer cells." (PMID 41226649, 2025). "Hence, the analysis of genotypes of young-onset vs. late-onset patients with breast cancer has a potential for identification of BRCA1 penetrance modifiers." (PMID 41374957, 2025). "Moreover, increased ADAT2 mRNA level is associated with poor prognosis in breast cancer patients and ADAT protein levels were found by immunohistochemistry staining to be higher in BRCA1 mutant compared with BRCA1 wild-type breast tumors." (PMID 40907939, 2025). "This threshold is clinically significant in ovarian and breast cancer, allowing the detection of 95% of BRCA1/2-positive tumors of these types and identifying patients who may benefit from PARP inhibitors and platinum drugs." (PMID 41465280, 2025). "In this study, we profiled and analyzed OR cells generated from two BRCA1/2 mutant breast cancer cell lines at the transcriptome, proteome, ADP-ribosylome, and phosphoproteome levels to investigate the changes they undergo when they acquire Olaparib resistance." (PMID 40669753, 2025). "In addition, the frequency of pathological genetic mutations in BRCA1 and BRCA2 in sporadic breast cancers in the South Korean population was found to be 3.1%." (PMID 40361383, 2025). "Consequently, germline (g)BRCA1 and BRCA2 mutations are associated with a lifetime risk of breast cancer of up to 72%." (PMID 39392573, 2025). "In the second application, the sample is composed of women with a family history of breast cancer and without BRCA1 or BRCA2 mutations." (PMID 40500950, 2025). "Additionally, Canagliflozin has been shown to upregulate BRCA1 while suppressing mTOR‐mediated inflammatory and pyroptotic signaling, reinforcing its therapeutic potential in breast cancer management." (PMID 41523619, 2025). "The alteration of BRCA1 reduces the expression of nuclear β-catenin, which may participate in breast cancer pathogenesis." (PMID 40001953, 2025).
breast cancer (continued). "The screening performed well, especially in women at high risk of aggressive BRCA1-associated breast cancer, by detecting invasive tumors ≤1 cm without nodal involvement and effectively avoiding interval invasive cancers with low recall rates." (PMID 39858629, 2025). "In breast cancer, the BRCA1/ZBRK1 complex represses GOT2 promoter activity, suggesting that BRCA1 loss-of-function may upregulate GOT2 by removing this repression." (PMID 40842990, 2025). "BRCA1-associated breast cancers also have higher risk to form TNBCs as an ~48% of BRCA1 mutation carriers develop TNBCs, compared with 12% of non-carriers." (PMID 41318657, 2025). "While in the context of breast cancer, it is classically used to treat cases of triple-negative disease, emerging evidence supports the experimental and clinical relevance of cisplatin in ER+ breast cancer models, particularly in tamoxifen-resistant or BRCA1-mutant contexts." (PMID 40869421, 2025). "All breast cancer patients in the universal testing group underwent BRCA1, BRCA2 and PALB2 testing." (PMID 41568010, 2025). "While our in vivo data highlight the plasticity of Fgfr2-mutant HP5008 and Brca1-mutant 545 cells, further investigations using additional ERα+ cell lines are warranted to determine if this phenotypic shift is a common feature of ERα+ breast cancers." (PMID 41318657, 2025). "Our findings offer preliminary evidence that pregnancy after breast cancer treatment does not appear to adversely affect maternal prognosis, even in BRCA1/2 mutation carriers." (PMID 41002733, 2025). "In addition, a family history of ovarian cancer, particularly in cases involving BRCA1 or BRCA2 mutations, is also a recognized risk factor for breast cancer." (PMID 40800071, 2025). "To investigate the role of TLK expression in modulating cell death following PARP inhibition or deficiency in BRCA1-deficient cancers, we categorized breast cancer cell lines from the CCLE based on the presence or absence of BRCA1 mutations." (PMID 39844055, 2025). "The main outcome was prevalence of P/LP variants in BRCA1 and BRCA2 in women with breast cancer." (PMID 40952741, 2025). "Not all patients carrying BRCA1-deficient breast cancer responded equally well; some patients experienced relevant side effects from PARP inhibitors, including myelosuppression, gastrointestinal toxicity, hypercholesterolemia, fatigue, and teratogenicity." (PMID 41155174, 2025). "Pathogenic variants of BRCA1 and BRCA 2 are the most frequent causes for hereditary breast cancer." (PMID 39621070, 2025). "In addition, GRP78 has been shown to be negatively regulated by the tumor suppressor BRCA1 in ovarian and breast cancer cells, while mutant BRCA1 enhances GRP78-mediated cell survival and resistance to apoptosis." (PMID 40959569, 2025). "Although we found that BRCA1-associated breast cancers were more likely to be early-stage and node-negative at presentation, they were also more likely to receive chemotherapy due to a higher prevalence of TNBC." (PMID 40275390, 2025). "Pre-diagnostic awareness of a germline pathogenic variant in BRCA1/2 or PALB2 allows for enhanced screening and risk-reducing mastectomy, the latter of which dramatically lowers the likelihood of being diagnosed with breast cancer." (PMID 40275390, 2025). "Our results confirm the previously established breast cancer risk-reducing effect of BRRM and suggest that the lack of statistical significance in the Danish study from 2010 was likely due to its small sample size of 307 BRCA1/2 carriers." (PMID 40974500, 2025). "In this pathway, BRCA1 was correlated with the mitogenic action of ESR1 in breast cancer cells." (PMID 40278313, 2025). "Prenatal BRCA1 epimutations also contribute to TNBC development, which may be the underlying cause of approximately 20% of TNBC and low-ER-expression breast cancers." (PMID 40573960, 2025).